PRDX6 (peroxiredoxin 6)
Description:
Thiol-specific peroxidase that catalyzes the reduction of hydrogen peroxide and organic hydroperoxides to water and alcohols, respectively. Can reduce H(2)O(2) and short chain organic, fatty acid, and phospholipid hydroperoxides. Also has phospholipase activity, can therefore either reduce the oxidized sn-2 fatty acyl group of phospholipids (peroxidase activity) or hydrolyze the sn-2 ester bond of phospholipids (phospholipase activity). These activities are dependent on binding to phospholipids at acidic pH and to oxidized phospholipds at cytosolic pH. Plays a role in cell protection against oxidative stress by detoxifying peroxides and in phospholipid homeostasis. Exhibits acyl-CoA-dependent lysophospholipid acyltransferase which mediates the conversion of lysophosphatidylcholine (1-acyl-sn-glycero-3-phosphocholine or LPC) into phosphatidylcholine (1,2-diacyl-sn-glycero-3-phosphocholine or PC). Shows a clear preference for LPC as the lysophospholipid and for palmitoyl CoA as the fatty acyl substrate.
Synonyms: aiPLA2; LPCAT-5; NSGPx; AOP2; KIAA0106; 1-Cys; PRX; MGC46173; p29; HEL-S-128m
Tractability: Antibody: its Gene Ontology location is reachable by antibodies, with high confidence. PROTAC: ubiquitination databases record sites on it; its protein half-life has been measured.
Target class: Enzyme; Oxidoreductase
Gene: Protein-coding gene on chromosome 1 (173,476,814 to 173,489,064, forward strand). Ensembl gene ENSG00000117592.
Subcellular location: Cytoplasm; Lysosome
Subcellular location (Human Protein Atlas): Cytosol; Plasma membrane
Pathways (Reactome):
Cellular responses to stimuli: Detoxification of Reactive Oxygen Species
Immune System: Neutrophil degranulation
Gene Ontology:
Molecular function: 1-acylglycerophosphocholine O-acyltransferase activity; cadherin binding; glutathione peroxidase activity; identical protein binding; phospholipase A2 activity; protein binding; ubiquitin protein ligase binding; peroxidase activity; antioxidant activity; oxidoreductase activity; peroxiredoxin activity
Biological process: cellular oxidant detoxification; glycerophospholipid catabolic process; positive regulation of mRNA splicing, via spliceosome; response to oxidative stress; cell redox homeostasis; hydrogen peroxide catabolic process
Cellular component: cytoplasm; cytosol; extracellular exosome; extracellular region; membrane; nucleus; perinuclear region of cytoplasm; azurophil granule lumen; lysosome
Genetic constraint (gnomAD): Loss-of-function variants: 13 observed, 21.08 expected, observed/expected ratio (o/e) 0.62, 90% interval 0.4 to 0.98. The upper end of that interval is the gene's LOEUF score, 0.98, which puts it in group 4 of 6, group 1 being the genes least tolerant of losing a copy. Missense variants: 203 observed, 289.23 expected, observed/expected ratio (o/e) 0.7, 90% interval 0.62 to 0.79. Synonymous variants: 85 observed, 104.15 expected, observed/expected ratio (o/e) 0.82, 90% interval 0.68 to 0.98.
Homologues: Orthologues: chimpanzee PRDX6 (100% identical), macaque PRDX6 (99% identical), guinea pig PRDX6 (96% identical), dog PRDX6 (93% identical), pig PRDX6 (93% identical), rat Prdx6 (92% identical), mouse Prdx6 (90% identical), mouse Prdx6b (79% identical), tropical clawed frog prdx6 (77% identical), Drosophila melanogaster Prx6b (52% identical), Drosophila melanogaster Prx6c (52% identical), Drosophila melanogaster CG12896 (51% identical). Paralogues in human: PRDX1 (29% identical), PRDX2 (29% identical), PRDX4 (27% identical), PRDX3 (25% identical).
Diseases named in the same sentence as PRDX6 in open-access papers:
PRDX6 is named in the same sentence as 181 diseases in open-access papers, as found by Europe PMC text mining. Sharing a sentence is not in itself a finding about the gene and the disease. The quoted sentences say what the papers report.
lung carcinoma (36 papers, 2011 to 2025). "It has been reported that PRDX6 is associated with the occurrence and progression of esophageal cancer, ovarian cancer, melanoma, prostate cancer, lung cancer, and colorectal cancer." (PMID 38544826, 2024). "Studies suggest that a decrease in the prevalence of malignant lung tumors in Alzheimer’s patients with presenilin-2 mutations is associated with increased PRDX6 degradation." (PMID 36611974, 2023). "With regard to PRDX6, its over-expression was associated with carcinogen-induced tumor incidence 79 and tumor-progression 80 in lung cancer." (PMID 32231717, 2020). "It was also reported that PRDX6 expression in lung cancer cells was significantly associated with tumor progression." (PMID 24618722, 2014). "Since PRDX6 is implicated in lung cancer cell growth, we investigated whether interaction of thiacremonone and PRDX6 could inhibit PRDX6 activity, thereby inhibit cancer cell growth." (PMID 24618722, 2014). "As an example, overexpression of peroxiredoxin 6 promotes the growth of lung cancer cells by upregulating AP-1 and JNK, thus increasing some peroxidases and phospholipase A2 activities." (PMID 41187427, 2025). "Specifically, PRDX6-Gpx activity facilitates lung cancer growth while its aiPLA2 activity enhances invasiveness." (PMID 40298631, 2025). "The silencing of PRDX6 in epithelial and tumor cell lines such as H1299, A549, and 293FT and lung cancer cells significantly enhanced ferroptosis induced by erastin." (PMID 39061949, 2024). "Thiacremonone inhibits the growth of lung cancer cells by inhibiting the peroxidase of PRDX6 by interacting with the Cys-47 of PRDX6." (PMID 36611974, 2023). "Immunofluorescence showed increased co-localization and an interaction between PRDX6-transgenic mice and lung cancer patients." (PMID 36611974, 2023). "Compared with wild-type mice, the phosphorylation of JAK2 and STAT3 in the lung cancer tissues of PRDX6-transgenic mice were significantly increased." (PMID 36611974, 2023). "PRDX6 is upregulated in various human cancers such as esophageal squamous cell carcinoma, colorectal cancer, ovarian cancer, lung cancer, skin cancer and cervical cancer." (PMID 36209344, 2022). "In lung cancer cells, it has been demonstrated that the upregulation of PRDX6 results in the activation of Akt via phosphoinositide 3-kinase (PI3K) and p38 kinase." (PMID 36361777, 2022). "In lung cancer, PRDX6 promotes tumor development by regulating redox-sensitive pathways such as JAK/STAT, MAPK, AP-1 and JNK." (PMID 36209344, 2022). "To verify the roles of Notch3 in tumorigenesis and the relationship of Notch3 with GPX4 and PRDX6, we established an in vivo xenograft model using Notch3 knockdown lung cancer cells." (PMID 35258176, 2022). "PRDX6 is overexpressed in a variety of cancers and is involved in the tumor progression of different tumors, such as lung cancer, thyroid, and colorectal cancer." (PMID 34616431, 2021). "The mRNA levels of PRDX1, PRDX2, PRDX3, PRDX5, and PRDX6 showed an excellent correlation with the OS of lung cancer patients." (PMID 32908916, 2020). "Some researchers 38 demonstrated that PRDX6 significantly stimulates the invasion of lung cancer cells, inducing the expression of urokinase-type plasminogen activator." (PMID 32201510, 2020). "In our previous study 82, we have evaluated the serum level of PRDX6 and it was shown to be higher in lung cancer while lower in colon cancer than their healthy controls." (PMID 32231717, 2020). "A specific inhibitor of Prdx6, thiacremonone discovered recently in garlic extract, is a dose-dependent suppressor of lung cancer cell growth (lines A549 and NCI-H460), which acts through triggering apoptosis." (PMID 30621289, 2019). "The Keap1/Nrf-2/ARE pathway-mediated upregulation of Prdx6 mRNA expression has been reported in human lung carcinoma cells (A549) and primary rat alveolar type II cells treated with H2O2 or tert-butylhydroquinone." (PMID 31527445, 2019).
lung carcinoma (continued). "As well, the tumor promoter role of PRDX6 in cancers has also been suggested in colorectal cancer, lung cancer and so on." (PMID 31402980, 2019). "Prdx6 plays an important role in oxidative stress response as its overexpression in lung carcinoma cells (NCI-H441) reduced cellular OH- levels, and attenuated membrane phospholipid peroxidation and apoptosis induced by Cu2+-ascorbate treatment." (PMID 31527445, 2019). "Increased Prdx6 levels have been detected in various cancers, and the role of Prdx6 in lung cancer invasion is well known." (PMID 30477202, 2018). "Peroxidase activity of Prdx6 facilitates the growth of lung cancer cells, and PLA2 activity promotes invasiveness." (PMID 28596967, 2017). "In the present study, we evaluated anti-tumor effects of SVT in lung cancer cells through blunting AP-1 activity of PRDX6." (PMID 26061816, 2015). "We also found that PRDX6 expression was significantly lower in the SVT treated cultured human lung cancer cells as wells as xenograft tumor tissues." (PMID 26061816, 2015). "It was reported that the increased Prdx6 activity promotes the growth of lung cancer cells and enhances the metastatic potential of lung cancer cells." (PMID 26273424, 2015). "To further determine the relationship between PRDX6 expression and lung cancer cell growth inhibitory effect of SVT, we transfected A549 and NCI-H460 cells with c-Fos siRNA using a transfection agent." (PMID 26061816, 2015). "Our present findings showed that SVT inhibited lung cancer cell growth through the inhibition of PRDX6 activity via interaction to AP-1." (PMID 26061816, 2015). "Several studies have demonstrated that PRDX6 stimulates lung cancer cell growth via an increase of glutathione peroxidase activity." (PMID 24618722, 2014). "The invasion and metastasis promoting actions of PRDX6 has been found in lung cancer cells through activation of Akt via activation of phosphoinositiede 3-kinase (PI3K) and p38 kinase." (PMID 24618722, 2014). "The activity of PRDX6 contributes to the metastatic ability of lung cancer cells by stimulating invasion components including PI3K, Akt, and uPA." (PMID 24618722, 2014). "The results indicated that thiacremonone bound with recombinant PRDX6 protein or cell lysates containing PRDX6 protein from human NCI-H460 lung cancer cells." (PMID 24618722, 2014). "A recent studied demonstrated that PRDX6 promotes lung cancer metastasis and invasion via phospholipase A2 activity in mice." (PMID 21627785, 2011). "The increased levels of GSTO1 and PRDX6 in plasma of lung cancer patients may reflect their protective role in the cancer redox environment, or may be associated with the activation of antioxidant pathways resulting from cigarette smoking." (PMID 32575471, 2020). "In conclusion, our result that natural toxin SVT could be useful as an anti-lung cancer agent through inhibiton of PRDX6 by the interaction with AP-1 which inhibited expression of PRDX6." (PMID 26061816, 2015). "Thus, it is possible that SVT binds to the cysteine residue of its transcription factor AP-1 in PRDX6, and as a result, the inactivation of PRDX6 inhibits lung cancer cell growth." (PMID 26061816, 2015). "Since AP-1 is implicated in tumor growth and PRDX6 expression, in the present study, we investigated whether SVT inhibits PRDX6, thereby preventing human lung cancer cell growth (A549 and NCI-H460) through inactivation of AP-1." (PMID 26061816, 2015). "Peroxiredoxin 6 (PRDX6) is known to be a stimulator of lung cancer cell growth." (PMID 26061816, 2015). "Consistent with this assumption, thiacremonone, a compound isolated from garlic, was shown to bind to the catalytic site Cys47 of Prdx6 and it reduced the tumor volume of lung carcinoma cells allografted to wild-type mice and in particular of cells allografted to Prdx6 transgenic mice." (PMID 25594034, 2014). "Overexpression of PRDX6 increased lung cancer cell growth via activity of PRDX6." (PMID 24618722, 2014).
lung carcinoma (continued). "Peroxiredoxin-6 (antioxidant protein 2), 2.6 fold elevated in colonic fibroblasts and 2.1 fold elevated in colonic crypts, is an anti-oxidative protein with phospholipase A2 activity that can promote the invasiveness of lung cancer cells." (PMID 21411865, 2011). "Therefore, PRDX6 may enhance the stem-like properties of CSCs and mediate chemotherapy resistance in lung cancer by maintaining a low level of ROS through anti-oxidation." (PMID 36611974, 2023). "The results exhibited that PRDX6 could regulate the cell proliferation through JAK2-STAT3 pathway and is implicated in the process of cell cycle, which were in consistent with the results from lung cancer model." (PMID 34246267, 2021). "In our study, PRDX6 was low expressed in QDLS lung cancer, and have a significant difference between the two syndromes, implying that PRDX6 focused on the influence of invasion ability and phospholipid metabolism homeostasis with “Yin deficiency” in the two groups of lung cancer." (PMID 34838074, 2021). "Thus, inhibition of AP-1 by SVT could be significant for reduced PRDX6 activity, and thus decreased lung cancer cell growth." (PMID 26061816, 2015). "Thus, we investigated whether thiacremonone inhibits cell growth by blocking glutathione peroxidase of PRDX6 in the human lung cancer cells, A549 and NCI-H460." (PMID 24618722, 2014). "Knockdown of Notch3 can increase the ROS level in lung cancer cells, reduce the expression levels of GPX4 and peroxiredoxin 6 (PRDX6), and then induce lipid peroxidation to trigger cell ferroptosis." (PMID 37005430, 2023). "Studies in animal models of lung cancer (A549 and NCI-H460) demonstrated effective dose-dependent alleviation of Prdx6 level and apoptosis stimulation by SVT." (PMID 30621289, 2019). "Meanwhile, Prdx6 interacts directly with JAK2 protein, as immunohistochemical analysis showed colocalization of these proteins in lung cancer cells." (PMID 30621289, 2019). "Our present results showed that expression of PRDX6 via inactivation of AP-1 in A549 and NCI-H460 lung cancer cell were decreased." (PMID 26061816, 2015). "In the present study, we found that SVT inhibited cell growth of human lung cancer cells; A549 and NCI-H460 through the inhibition of PRDX6 activity via interaction to AP-1." (PMID 26061816, 2015). "Finally, in another recent study, the protein levels of PRDX6 (and ACSL3) were found to be higher in tumor tissues of lung adenocarcinoma, implicating a possible role of PRDX6 in ferroptosis resistance in lung cancer cells." (PMID 38539832, 2024). "Recent studies have demonstrated that PRDX6 could activate Akt through the activation of phosphoinositide 3-kinase (PI3K) and p38 kinase, and further induce uPA (urokinase plasminogen activator) to promote the invasion of lung cancer cells." (PMID 34838074, 2021).
breast carcinoma (25 papers, 2007 to 2025). "Our analysis revealed that mutations in OSRE such as MGST3, GSTP1, NDUFS2, NDUFS8 and PRDX6 were particularly prevalent in breast cancer, and for the five genes the most prevalent genetic alteration was amplification." (PMID 39594421, 2024). "Previous studies report that the augmented levels of PRDX1, PRDX3 and PRDX6 were associated with cisplatin resistance status for erythroleukemia, breast cancer and ovarian carcinoma." (PMID 34246267, 2021). "A significant association between PRDX6 staining and the presence of lymph-node metastasis in 80 breast cancer donors was also observed." (PMID 17980029, 2007). "Besides, the PRDX6 rs4916362 which is located at a transcription factor binding site, and PRDX6 rs7314 placed at a miRNA binding site, may modify the mortality risk in breast cancer patients." (PMID 33672092, 2021). "In human breast cancer cell lines, peroxiredoxin 6 overexpression leads to a more invasive phenotype, increased metastatic potential, and drug resistance." (PMID 41187427, 2025). "PRDX6 participated in protection against oxidative injury and the suppression of PRDX6 increased the peroxide-induced cytotoxicity in breast cancer cells." (PMID 38577609, 2024). "Unique mutations in genes such as NDUFS2, MGST3, PRDX6, NDUFS8, and GSTP1 were found predominantly in breast cancer." (PMID 39594421, 2024). "Given the fact that PRDX6 is overexpressed predominantly in breast cancer, lung adenocarcinoma, and melanoma, their malignant phenotype may be associated with the anti-ferroptotic action attributed to the intrinsic activities of PRDX6 toward peroxidized phospholipids." (PMID 35326151, 2022). "Overexpression of PRDX6 leads to a more invasive phenotype and metastatic potential in human breast cancer." (PMID 23724044, 2013). "PRDX6 protects against oxidative injury, it is overexpressed in endometriosis and it increases the invasiveness of breast cancer." (PMID 22415234, 2012). "Overexpression of peroxiredoxin 6 leads to a more invasive phenotype and metastatic potential in human breast cancer, at least in part, through regulation of the levels of uPAR, Ets-1, MMP-9, RhoC and TIMP-2 expression." (PMID 17980029, 2007). "All these results indicate that PRDX6 promotes breast cancer progression, partially through upregulation of uPAR, Ets-1, MMP-9 and RhoC expression and downregulation of TIMP-2 expression." (PMID 17980029, 2007). "In this study, we have demonstrated that upregulated expression of the uPAR, but not uPA, was associated with increased tumor cell invasion and metastasis in breast cancer by PRDX6." (PMID 17980029, 2007). "By contrast, peroxiredoxin 6 knockdown breast cancer cells grew more slowly and had fewer pulmonary metastases." (PMID 17980029, 2007). "We found that the expression of PRDX6 was significantly decreased in pCMV-PRDX6 miRNA-672 groups of breast cancer cells." (PMID 17980029, 2007). "Upregulation of peroxiredoxin 6 enhanced the in vitro proliferation and invasion of breast cancer cells." (PMID 17980029, 2007). "In the present study, we demonstrated that the enhancement of invasive phenotype of breast cancer cells by PRDX6 was accompanied by upregulation of MMP-9 and Ets-1 expression and downregulation of TIMP-2 expression." (PMID 17980029, 2007). "By contrast, PRDX6 knockdown cells showed decreased ability in breast cancer growth, invasiveness, and metastasis." (PMID 17980029, 2007).